SMAD7 (SMAD family member 7)
Diseases named in the same sentence as SMAD7 in open-access papers (continued):
Sharing a sentence is not in itself a finding about the gene and the disease.
heart failure (10 papers, 2013 to 2025). Inability of the heart to pump blood at an adequate rate to meet tissue metabolic requirements. "In heart failure, miR-21 acts to prevent apoptosis and promotes fibrosis and hypertrophy via the TGFβ-associated Smad7 and sprouty homolog (Spry1/2) proteins." (PMID 38485860, 2024). "Cell-specific loss-of-function approaches showed that myofibroblast Smad7 protects the infarcted heart from heart failure–related mortality and from adverse remodeling, limiting fibrosis in the infarct border zone and in the papillary muscles." (PMID 34905511, 2022). "Myofibroblast-specific Smad7 loss increased heart failure–related mortality, worsened dysfunction, and accentuated fibrosis in the infarct border zone and in the papillary muscles." (PMID 34905511, 2022). "Myofibroblast-specific Smad7 loss increases heart failure–related mortality in infarcted mice." (PMID 34905511, 2022). "The lncRNA NEAT1 recruits EZH2 to the Smad7 promoter, increases Smad7 methylation, and accelerates the development of heart failure and ventricular remodeling." (PMID 38584203, 2024). "First, Smad3-mediated Smad7 overexpression in infarct myofibroblasts is an important endogenous protective mechanism that reduces heart failure–related mortality and limits maladaptive ventricular fibrosis." (PMID 34905511, 2022). "With regard to the underlying mechanism, our findings showed that Neat1 promoted the progression of cardiac fibrosis to heart failure by recruiting EZH2 to the promoter region of Smad7." (PMID 34980170, 2022). "Our findings show that myofibroblast-specific Smad7 induction serves as a crucial endogenous inhibitory signal in restraining fibrotic remodeling and dysfunction following MI and reduces heart failure–related mortality." (PMID 34905511, 2022). "Mortality data and functional echocardiographic analysis show that myofibroblast-specific Smad7 protects the infarcted heart from adverse remodeling and reduces heart failure–related mortality." (PMID 34905511, 2022). "Studies using cell-specific knockout mice demonstrated that myofibroblast Smad7 expression protects the infarcted myocardium from heart failure and attenuates adverse remodeling and fibrosis by restraining collagen accumulation and myofibroblast conversion." (PMID 35563692, 2022). "Induction of TGF-β1 by high glucose or Ang-II, which then phosphorylates and activates downstream Smad2 and Smad3 proteins, results in cardiac fibrosis, cardiac hypertrophy and heart failure; however, Smad7 can antagonize TGF-β–mediated cardiac remodeling." (PMID 23690953, 2013). "By downregulating Smad7, LINC00152 aggravates heart failure following AMI via promoting the proliferative and migratory abilities in cardiac fibroblasts." (PMID 34900025, 2021). "In heart failure, lncRNA NEAT1 was found to provide scaffolding between the enhancer of zeste homolog 2 (EZH2) and the Smad7 promotor region similar to lncRNA MALAT1, thereby decreasing the expression of Smad7 and leading to unbalanced TGFβ–driven fibrosis." (PMID 38485860, 2024).
Ureteral obstruction (10 papers, 2005 to 2024). Obstruction of the flow of urine through the ureter. "On this basis, we examined the effect of BET inhibition on the phosphorylation of Smad3 and expression of Smad7 in the kidney after ureteral obstruction." (PMID 27732564, 2016). "It is reported that reduction of Smad7 due to the overexpression of Smurf1 in unilateral ureteral obstruction kidneys plays an important role in the progression of tubulointerstitial fibrosis, which a harmful process leading inevitably to renal function deterioration." (PMID 24997640, 2014). "In a unilateral ureteral obstruction-induced tubulointerstitial damage and fibrosis model, the expressions of TGF-β1 and CTGF were significantly reduced by Gyps treatment, and the Smad7 expression was elevated by Gyps treatment." (PMID 35095515, 2021).
asthma (9 papers, 2010 to 2022). "In our study, EP300, ID1, ID3, SMAD2, and SMAD5 were DC with a loss of connectivity, whereas SMAD7 exhibited a network connectivity gain due to asthma." (PMID 34257337, 2021). "The expression of Smad7 in the lung tissue was increased in both the asthma group and the mycobacterium nebulization group." (PMID 32834825, 2020). "The Smad7 transgenic animals significantly protected from OVA-induced asthma, with reduced airway inflammation, airway mucus production, extracellular matrix deposition, and production of OVA-specific IgE." (PMID 20405019, 2010). "In contrast to the protective role of Smad7 overexpression in OVA-induced asthma, blocking TGF-β signaling by overexpression Smad7 specifically in Clara cells was sufficient to increase the incidence of lung carcinogenesis following exposure to urethane." (PMID 20405019, 2010). "Using the OVA-induced asthma model, we analyzed the role of Smad7 in the development of allergic asthma." (PMID 20405019, 2010). "Previous study revealed that expression of Smad7 in bronchial epithelial cells is inversely correlated to basement membrane thickness and airway hyperresponsiveness in patients with asthma." (PMID 20405019, 2010). "Some other cytokines that were previously found to be related to asthma development such as G-CSF, GM-CSF and IP-10, had consistent change toward a favorite direction in the Smad7 transgenic mice, indicating a reduced allergic development." (PMID 20405019, 2010). "In contrast to the protective role of Smad7 on asthma development, CC10-Smad7 mice showed significantly increased incidence of lung tumors in comparison with the wild type controls." (PMID 20405019, 2010). "extract treated mice when compared with asthma mice (data not shown), which suggests that Smad7 expression is not targeted by extract for inhibiting TGF-β signaling." (PMID 27073403, 2016). "And transgenic mice with selective expression Smad7 in mature T cells to block TGF-β signaling in T cells enhanced airway inflammation and airway reactivity However, most of these studies are mainly focused on the function of TGF-β in immune cells to the development of asthma." (PMID 20405019, 2010). "To better understand whether or not TGF-β signaling in epithelial cells contributes to asthma development, we expressed Smad7 in mouse airway progenitor cells using a mouse Clara cell specific 10 kDa protein (CC10) promoter to specifically block TGF-β signaling pathway in airway epithelial cells." (PMID 20405019, 2010).
cardiac hypertrophy (9 papers, 2010 to 2025). "In the cardiovascular system, miR-410-3p promotes Ang II-induced myocardial hypertrophy by inhibiting Smad7." (PMID 40504789, 2025). "Mechanistically, miR-410-3p mediated Smad7 down-regulation was demonstrated to be an essential process in Ang II-provoked cardiac hypertrophy." (PMID 34951337, 2022). "Mechanistically, we provide evidence that miR-410-3p facilitates Ang II-provoked cardiac hypertrophy via down-regulation of Smad7." (PMID 34951337, 2022). "In summary, our findings revealed that miR-410-3p mediated Ang II–induced cardiac hypertrophy via targeting inhibition of Smad7." (PMID 34951337, 2022). "Importantly, we further observed that miR-410-3p induced cardiac hypertrophy via down-regulation of Smad7 and that Smad7 down-regulation was integral to the pro-hypertrophic effect of miR-410-3p." (PMID 34951337, 2022). "Moreover, long-term treatment with B-type natriuretic peptide significantly attenuated cardiac hypertrophy via the Smad7 pathway in vivo and in vitro." (PMID 21152044, 2010). "The results of the current study are consistent with the notion that cardiac hypertrophy is preceded by sharp upregulation in the mRNA expression levels of profibrotic markers (TGF-β, SMAD-2, SMAD-3, SMAD-4, and NF-κβ) and marked downregulation of antifibrotic SMAD-7 mRNA and let-7b miRNA." (PMID 36030321, 2022). "Curcumin treatment reduced cardiac hypertrophy, improved diastolic function and reduced extracellular matrix production, without affecting glycemic control, along with a reduction in TGF-β activity as assessed by Smad7 activation (all p < 0.05 c/w vehicle treated diabetic animals)." (PMID 24886336, 2014).
osteoporosis (9 papers, 2020 to 2024). A condition of reduced bone mass, with decreased cortical thickness and a decrease in the number and size of the trabeculae of cancellous bone (but normal chemical composition), resulting in increased fracture incidence. "Exosomes containing miR-21 in osteoporosis patients interfere with osteogenesis events by the potential targeting of small mothers against decapentaplegic homolog-7 (SMAD7)." (PMID 37190068, 2023). "In conclusion, GAS5 promotes osteoblast differentiation by targeting the UPF1/SMAD7 axis and protects against osteoporosis." (PMID 33006314, 2020). "The reduction of estrogen levels post-menopause may consequently impact the expression or functional activity of SMAD7, thereby exacerbating the progression of osteoporosis." (PMID 39840278, 2024). "Riveting on our findings, up‐regulation of miR‐497 or down‐regulation of LRG1 could activate TGF‐β signalling pathway as accompanied by increased TGF‐β1, Smad3, Smad4 and p‐Smad2/3 protein expression and reduced Smad7 protein expression in osteoporosis." (PMID 32975015, 2020). "Suppression of miR-92b-3p expression increased Nox4 and NF-κB levels, decreased Smad7, BMP2, and RUNX-2 genes and protein expression, and inhibited BMSC proliferation and osteoblast differentiation, resulting in worsened osteoporosis." (PMID 37239124, 2023). "The GAS5/SMAD7 axis and GAS5/miR-135a-5p/FOXO1 axis in MSCs are both involved in the development and prognosis of osteoporosis and will be described in greater detail in Section 4.1." (PMID 35155450, 2021). "In addition to its roles in the GAS5/SMAD7 and GAS5/miR-135a-5p/FOXO1 axes, GAS5 also had other regulatory effects in osteoporosis." (PMID 35155450, 2021). "Suppression of miR-92b-3p expression increased NADPH oxidase 4 (Nox4) and NF-κB levels, decreased Smad7, BMP2, and Runx2 gene and protein expressions, and inhibited bone marrow mesenchymal stem cell (BMSC) proliferation and osteoblast differentiation, resulting in more severe osteoporosis." (PMID 37239124, 2023).
Hypertension (8 papers, 2013 to 2025). The presence of chronic increased pressure in the systemic arterial system. "Lentivirus knockdown of SMAD7 prevented AngII-induced Smad3+/−Mir-21−/− mouse TAAD formation, and VSMC-specific miRNA-214 knockout inhibits AngII-induced hypertension through up-regulation of SMAD7." (PMID 35517795, 2022). "ANG II infusion produced equivalent hypertension in Smad7 KO and WT mice; however, Smad7 KO mice exhibited more severe renal functional injury as shown by increased proteinuria and reduced renal function (both p<0.05) when compared with Smad7 WT mice." (PMID 23301086, 2013). "The present study provided new evidence for a protective role of Smad7 in Ang II-induced hypertensive cardiac remodeling." (PMID 23894614, 2013). "However, the detailed mechanisms regarding SMAD7 expression and its role in kidney fibrosis in the context of hypertension and an HFD need to be thoroughly investigated." (PMID 40869353, 2025). "By affecting SMAD7, vascular endothelial growth factor, renin pathways, and subclinical inflammation, microRNA-21 is involved in the development and progression of hypertension and HMOD, including left ventricular hypertrophy and arterial damage measured by the cIMT and PWV." (PMID 39598074, 2024).
idiopathic pulmonary fibrosis (7 papers, 2017 to 2025). Idiopathic pulmonary fibrosis (IPF) is a nonneoplastic pulmonary disease that is characterized by the formation of scar tissue within the lungs in the absence of any known cause. "In dual-luciferase reporter gene assays, Smad7 was shown to be negatively regulated by miR-182-5p; therefore, inhibiting miR-182-5p can be regarded as an effective method for treating idiopathic pulmonary fibrosis (IPF)." (PMID 41426608, 2025).
Obesity (7 papers, 2013 to 2025). Accumulation of substantial excess body fat. "When Smads were overexpressed in high-fat diet (HFD)-fed obese mice using an adenoviral delivery system, Smads2/3/4 improved, but Smad7 worsened, obesity-associated metabolic parameters and inflammation in a MPK38 phosphorylation-dependent manner." (PMID 29700281, 2018). "We found that increased susceptibility to obesity in mice was associated with systemic hyperleptinemia and hypoestrogenism, the latter mediated by decreased ovarian steroidogenesis, particularly in TC, due to the inhibition of Nodal signalling by SMAD7." (PMID 39536822, 2024). "Furthermore, overexpression of Smads2/3/4 improves, whereas Smad7 overexpression worsens, obesity-associated metabolic parameters by differentially regulating MPK38 activity in HFD-induced obese mice." (PMID 29700281, 2018). "Overall, we confirmed that greater susceptibility to obesity in mothers leads to impaired ovarian steroidogenesis through decreased Nodal signalling activity and reduced support of steroidogenic machinery in the TC compartment, primarily driven by leptin-mediated upregulation of Smad7." (PMID 39536822, 2024). "Increased susceptibility to obesity in MO is associated with systemic hyperleptinemia and hypoestrogenism due to compromised ovarian steroidogenesis, largely driven by the inhibitory effects of leptin-Smad7 pathway on Nodal signalling activity in the TC compartment of ovarian follicles." (PMID 39536822, 2024). "Conversely, miR-92a demonstrates upregulated expression in states of obesity, and the inhibition of miR-92a has been shown to promote the differentiation of brown adipocytes and induce thermogenesis through its targeting of SMAD7." (PMID 40649784, 2025). "Two miRNAs up‐regulated in obesity and sarcopenia, miR‐424‐5p33 and miR‐92a‐3p,93 target Smad7, a strong inhibitor of the TGF‐β pathway, which in turn inhibits SMAD2/3." (PMID 34984856, 2022). "In contrast to the tumor-promoting profile of SMAD7 in obesity, FMN1 does not have a clear relationship with inflammation." (PMID 37249599, 2023).
rheumatoid arthritis (7 papers, 2010 to 2024). A chronic, systemic autoimmune disorder characterized by inflammation in the synovial membranes and articular surfaces. "TGF-β/Smad3 signaling pathway is activated in synovium of patients with rheumatoid arthritis, being involved with Smad7 deficiency, and enhancement of Th17 and Th1 immune response." (PMID 34526039, 2021). "Among top 20 up-regulated genes, Smad7 is the only one reported to inhibit Treg cell differentiation in rheumatoid arthritis upon up-regulation by the EZH2-FOXP3-RUNX1 axis." (PMID 37600496, 2023). "Smad7 is protective in a mouse model of rheumatoid arthritis." (PMID 36845150, 2023). "Among top 20 genes up-regulated in double E2-deficient Treg cells (group 4), Smad7 is the only one known to be involved in regulation of Treg cells, whose up-regulation by the EZH2-FOXP3-RUNX1 axis inhibited Treg cell differentiation in rheumatoid arthritis." (PMID 37600496, 2023). "Conversely, overexpression of Smad7 in the joint improves rheumatoid arthritis." (PMID 31929822, 2019). "However, the roles of Smad7 in rheumatoid arthritis (RA) remain unexplored, which were investigated in this study." (PMID 30450102, 2018).
Arthritis (6 papers, 2016 to 2023). Inflammation of a joint. "Further studies revealed that enhanced arthritis in Smad7 KO CD-1 mice was associated with increased Th1, Th2 and, importantly, Th17 over the Treg immune response with overactive TGF-β/Smad3 and proinflammatory IL-6 signaling in the joint tissues." (PMID 30450102, 2018). "Surprisingly, CD-1 mice with Smad7 deficiency developed severe arthritis including severe joint swelling, synovial hyperplasia, cartilage damage, massive infiltration of CD3+ T cells and F4/80+ macrophages, and upregulation of proinflammatory cytokines IL-1β, TNFα, and MCP-1." (PMID 30450102, 2018). "They used lentiviral vector-mediated Smad7 overexpression and intra-articular injection to treat collagen-induced arthritis in mice and showed that it alleviated the pathology of rheumatoid arthritis." (PMID 34059951, 2021). "This was supported by the finding that loss of Smad7 was associated with a marked activation of TGF-β/Smad3 signaling and the development of arthritis in patients with RA." (PMID 30450102, 2018). "At first, the expression of pSmad2/3 and Smad7 were analyzed in synovial tissues from arthritis patients." (PMID 27731365, 2016). "In addition, it was shown that the intra-articular overexpression of SMAD7 relieved experimental arthritis." (PMID 35213968, 2022). "Smad7 knockdown in CD-1 mice increases their sensitivity to collagen-induced arthritis." (PMID 34059951, 2021). "In contrast, intraarticular overexpression of Smad7 ameliorates experimental arthritis." (PMID 30450102, 2018). "Next, we examined an experimental arthritis model for synovial expression of pSmad2/3 and Smad7." (PMID 27731365, 2016). "In order to prove the concept that overexpressing Smad7 as a therapeutic strategy in rheumatoid joint, we performed the i.a. injection of lentiviral vectors in CIA mice during the progression of arthritis (all groups with 100% incidence in this study)." (PMID 27731365, 2016). "Experimental arthritis mice lacking SMAD7 developed severe arthritis, including joint swelling, synovial hyperplasia, bone destruction, and immune cell infiltration." (PMID 35309322, 2022).
atrial fibrillation (6 papers, 2016 to 2025). A disorder characterized by an electrocardiographic finding of a supraventricular arrhythmia characterized by the replacement of consistent P waves by rapid oscillations or fibrillatory waves that vary in size, shape and timing and are accompanied by an irregular ventricular response. "Atria-Enriched GJA5, KCNA5 and NPPA, RA-Enriched HCM4, MIR100HG, REC114 and SMAD7 and Ventricles-Enriched KCNJ2, MYH7, PHLDB2, RPL2L and SLC35F1 were associated with atrial fibrillation." (PMID 34088950, 2021). "Our results provide compelling evidence that the miR-21 specific degradation of Smad7 may decrease the inhibitory feedback regulation of TGF-β1/Smad signaling and serves as a new insight of the mechanism of atrial fibrosis in atrial fibrillation." (PMID 26968995, 2016).
chronic kidney disease (6 papers, 2013 to 2022). Impairment of the renal function secondary to chronic kidney damage persisting for three or more months. "OGG1 promotes fibrosis progression in chronic kidney disease by interacting with Smad7 to promote TGF-β1-induced cell transformation." (PMID 36620083, 2022). "In chronic kidney disease, TGF-β1 signaling upregulated the Smurfs and caused ubiquitin-dependent degradation of Smad7, which led to a decrease in Smad7 protein level." (PMID 32266267, 2020). "In chronic kidney diseases, many mediators such as TGF-β1 and ANG II are able to induce Smad7 mRNA expression, but Smad7 protein is degraded." (PMID 23301086, 2013).
diabetic cardiomyopathy (6 papers, 2020 to 2025). Diabetic cardiomyopathy is a disorder of the heart muscle in people with diabetes. "Thus, in diabetic cardiomyopathy, an increased level of miR-21 was associated with cardiac interstitial and perivascular fibrosis through NFκB/SMAD7 signaling pathway." (PMID 35118144, 2021). "In conclusion, the pathway of NF‐κB/miR‐21/SMAD7 regulated the process of EndMT in T1DM, in diabetic cardiomyopathy, which may be regarded as a potential clinical therapeutic target for cardiac perivascular fibrosis." (PMID 31680453, 2020).